CD4 (CD4 molecule)
Diseases named in the same sentence as CD4 in open-access papers (continued):
Sharing a sentence is not in itself a finding about the gene and the disease.
tumor (continued). "Nevertheless, the vaccine-induced CD4 response was sufficient to inhibit tumor progression, indicating the effectiveness of responses that do not involve CD8+ T cells." (PMID 36291752, 2022). "For example, MHC-II-expressing melanoma cells block the functions of tumour-infiltrating CD4+ T cells, thus evading the recognition and killing of the immune system." (PMID 35494015, 2022). "In lymph node biopsied of HL, a mass cytometry discovered a CD4+ regulatory T-cell rich and exhausted T effector tumor microenvironment." (PMID 36035394, 2022). "Flow cytometric staining of CD45.2-enriched tumor-derived cells further revealed that depletion of tumor-infiltrating CD4+CD25+Foxp3+ Tregs was accompanied by a more general and severe depletion of tumor-infiltrating CD4+ T cells." (PMID 35972798, 2022). "A build-up of CXCR3 + CD4 + T cells in the tumour microenvironment as well as in the mesenteric and tumour-draining lymph nodes is seen when a favourable GM is present at baseline prior to ICI." (PMID 35876944, 2022). "In contrast to the inflamed areas, the analysis of samples from tumor areas revealed sparsely distributed CD4- and CD11b-positive cells." (PMID 35563010, 2022). "After T-cell expansion, effector CD4+ T cells and CTLs migrate through the bloodstream and infiltrate the tumor, becoming critical cells for tumor destruction." (PMID 36072935, 2022). "On the other hand, the mice injected with Olfr29‐ps1‐overexpressing MDSCs exhibited faster tumor development, larger tumor volume, heavier tumor weight, and fewer CD4+ and CD8+ T cells respect to control mice." (PMID 34080276, 2022). "Similar to CD8+ cytotoxic CAR T cells, CD4+ CAR T cells formed comparable numbers of conjugates with MDA-MB-453 tumor cells." (PMID 36591284, 2022). "While CD4+ Tregs are well characterized and known to promote tumor immune evasion, the fingerprint of CD4+ Th cells that recognizes tumor antigens and serves to restrict disease progression has remained poorly discriminated." (PMID 35703176, 2022). "In our previous study, cryo-thermal therapy was reported to induce Th1-dominant CD4+ T-cell-mediated antitumor immunity and improve the long-term survival rates of tumor-bearing mice." (PMID 36389684, 2022). "Mirza and his colleagues showed that ATRA promoted differentiation of immature myeloid cells and improve tumor-specific immune response mediated by both CD4 and CD8 T cells." (PMID 35493504, 2022). "The increased understanding of the role of CD4+ T cells as an integral part of anti-tumor immune response allowed us to explain the significant increase in the infiltration of CD4+ cells along with the improved anti-tumor potential of combination treatment." (PMID 36605208, 2022). "The antitumor status of the TIL infiltrates measured as CD8/CD4 reported higher values in the IM of encapsulated metastases up to 400 μm towards the tumor center (p < 0.05)." (PMID 35158957, 2022). "Independent from the presence of whole platelets, platelet-derived mediators released upon tumour cell-mediated platelet activation were also sufficient to amplify the differentiation of CD4+ T cells to an immunosuppressive phenotype." (PMID 35285006, 2022). "M2 macrophages directly inhibit CD4+ T cell-mediated tumor killing through cell-cell contact or release TGF-β and IL-10 and accelerate lymphatic tumor metastasis." (PMID 36072667, 2022). "Cibersort algorithm showed that T cells, including CD8+ T cells, CD4+ T cells and regulatory T cells, were lower in tumour tissues than para-tumor tissues." (PMID 35530333, 2022). "Blocking A2AR in vivo using the antagonist SCH58261 inhibited tumor growth, induced the decrease of CD4+ Foxp3+ Treg cells, and enhanced the antitumor response of T cells." (PMID 35386701, 2022). "Then, naive CD4 + T cells were cultured with AIL-treated tumor supernatant under Treg-prone conditions for 3 days." (PMID 36522774, 2022).
tumor (continued). "Within the tumor, the highest Itgb8 expression levels were observed in CD4+ T cells, particularly in CD4+CD25+ Tregs compared to conventional CD4+CD25− T cells." (PMID 36382146, 2022). "Along with T cell mediated anti-tumor effects, BAFF also induced CD4+FoxP3+ Treg population in the spleen and tumor microenvironment." (PMID 36159874, 2022). "The levels of tumor-infiltrated CD4- and CD8-positive T cells in the VV pre-immunized group were higher compared with the PBS pre-immunized group." (PMID 35615262, 2022). "In line with this in vitro evidence, our murine studies have also demonstrated that NFAT5 expression in tumor-infiltrating CD4+T cells was increased in the HS diet cohort more than in the NS and LS diet cohorts." (PMID 35741331, 2022). "In the HPV58 tumor-bearing mice, the CD4+/CD8+ ratio of the vaccine group were significantly decreased, while the CD8+ lymphocyte ratio was significantly increased compared with those of the PBS blank control group and the AD-NC group (P < 0.05)." (PMID 35197089, 2022). "We further show that cross-presenting cDC1s are indispensable for a functional anti-tumor CD8+ T cell response and tumor clearance, but also NDV-induced type I IFNs and CD4+ T cells play complementary roles in promoting optimal anti-tumor immunity." (PMID 36418317, 2022). "Analysis of immune cells in tumor tissues showed that the proportion of CD4+ T cells was higher in the tumors of B. microti-infected mice than in the uninfected mice." (PMID 35814662, 2022). "The anti-tumor effects of VTX-2337 plus cetuximab were accompanied by increased splenic lymphoid DCs, IFNγ+ CD4+ and tumor-specific CD8+ T cells." (PMID 36476317, 2022). "While IL-18 also has a tumor-suppressive effect that it was shown to activate CD4+T cells and NK cells and suppress the progression of tumor metastasis." (PMID 36237303, 2022). "There appears to be a decrease in TIM-3 expression on the surface of tumour-infiltrating CD4+ T cells post-FLOT chemotherapy (p = 0.06) and post-CROSS chemoradiotherapy compared with the treatment-naïve setting (p = 0.07)." (PMID 35366537, 2022). "CAFs upregulate PD-1, CTLA-4, TIM-3, and LAG-3 expression on both CD8+ and CD4+ T cells, resulting in hampered proliferation of T cells and impaired recognition of tumor cells in pancreatic cancer." (PMID 36700220, 2022). "Cellular neighborhoods revealed spatial organization of the tumor microenvironment, and local enrichment of PD-1+/CD4+ T cells was positively correlated with survival in high-risk patients." (PMID 39871933, 2022). "Here we report that exposure of human CD4+ and CD8+ T cells to tumor-associated succinate concentrations suppresses degranulation and cytokine secretion, including of the key anti-tumor cytokine interferon-γ (IFN-γ)." (PMID 35977513, 2022). "Meanwhile, the tumor-infiltrating CD4+ and CD8+ T cells of the QHF + ADM group were remarkably increased." (PMID 35818037, 2022). "The CD4 mRNA in the tumor region of ADC and SCC patients is reported to be lower than that of the control group and peritumoral region, respectively." (PMID 35719927, 2022). "Consistent with the results of the 24-gene validation experiment, EP300-KO CD4+ T cells killed target tumor cells significantly more quickly than did WT cells." (PMID 35990699, 2022). "The classification of BCC as a cold tumour is supported by another study showing a high stromal FoxP3+ to CD4+ T cell proportion, with a mean of 45%, concordant with our finding of 51.3%." (PMID 36552993, 2022). "On the other hand, CD4+ T cells can kill tumor cells directly through the IFN- γ mechanism even in the absence of CD8+ T cells." (PMID 35402261, 2022). "CXCL13-producing CD4+ T cells induced by tumor environments such as TGF-β are important for the initial formation of TLS." (PMID 35552285, 2022).
tumor (continued). "Another group demonstrated that targeting CXCR4 and PD-1 concurrently showed promise in murine models, with the combination regimen leading to decreased MDSC infiltration and improved CD4/CD8 T cell ratios in the tumor." (PMID 35690784, 2022). "This combination was associated with reduced numbers of tumor-promoting myeloid cells (induced apoptosis of MDSCs) alongside significant increases of active CD8+ and CD4+ T cells." (PMID 36551637, 2022). "We identify a robust population of tumor-infiltrating, clonally expanded CD4+ T cells expressing a canonical cytotoxic gene program." (PMID 35831288, 2022). "The results showed that TS with the dosage of 5 mg/kg not only increased the infiltration of CD4+ T cells in tumor tissue, but also increased the infiltration of CD8+ T cells, which is more obvious in 7.5 mg/kg group." (PMID 35577774, 2022). "With respect to MHC-II neoantigens, CD4+ regulatory T cells (Tregs) in the tumor showed the tumor reactivity, especially for neoantigens." (PMID 35269735, 2022). "The abscopal effect induced was strongest when 8 Gy × 3 fractions were delivered with concurrent drug treatment, which led to significantly increased tumor infiltration by CD4+ and CD8+ T cells at distant sites." (PMID 35804917, 2022). "Some studies have shown that an increase in CD4 cells in the tumor microenvironment before treatment predicts a better prognosis." (PMID 35711924, 2022). "Albeit significant only for one tumor region, namely, for the stromal internal region, we detected a general tendency for cases with a lower CD4+/CD8+ ratio exhibiting longer DMFS, indicating that higher CD8+ T cell accumulation is favorable for the patients." (PMID 35454849, 2022). "Based on the summary of literature data, tumor growth facilitates the induction and recruitment of CD4+ regulatory T cells that secrete IL-10 and TGF-β and suppress effector CD8+ T cell responses." (PMID 36194602, 2022). "When Xcr1-Cre was used to delete either MHC-II or CD40, tumor rejection was severely reduced, which suggests that a cognate interaction between CD4 T cells and cDC1s is required, at least to realize the full effect of CD8 T cell priming." (PMID 34480145, 2022). "IFNγ secreted by CD4+ T cells to my induce the expression of interferon-gamma-induced protein 10 (IP-10) and/or monokine induced by IFNγ (Mig) on tumor cells or stroma, leading to inhibition of angiogenesis." (PMID 36159781, 2022). "Some of these immune cell types such as CD8 + T cells, CD4 + T cells and plasma cells are directly involved in tumour immune response." (PMID 35904677, 2022). "Another ACT study of immune cells from TCR-tg mice found that CD4+ T cells were more efficient at tumor rejection than CD8+ T cells in vivo in 6 different tumor models and required MHC-II expression by host tissue, but not tumor, for clearance." (PMID 36159781, 2022). "Larger tumor size and/or LN involvement were associated with lower frequencies of CD4+TNF-α+, CD8+IFN-γ+ and CD8+IFN-γ+TNF-α+ but higher frequency of CD4+IL-4+ T cells." (PMID 36376825, 2022). "The activity of CD4 Th1 cells potentiates anti-tumor responses from NK and M1-type macrophages, which further promotes tumor killing causing the release of more TAAs for T cell priming." (PMID 36362027, 2022). "A2AAR blocking using SCH58261, an A2AAR antagonist, inhibited the tumor growth, reducing CD4+ and regulatory T cells, and improving the anti-tumor response by T cells." (PMID 36011024, 2022). "Next, we wanted to determine if NFAT5 knock out reduced the anti-CTLA4-mediated anti-tumor activation of CD4+T cells." (PMID 35741331, 2022). "Improved activation and anti-tumor immunity via GITR engagement in CD4+ TIL are described to be mediated either by CD4+ Treg depletion via Fcγ-receptor co-engagement on innate immune cells or CD4+ Treg functionality impairment via lineage destabilization." (PMID 36155259, 2022).
tumor (continued). "These immunosuppressive mechanisms affect tumor-infiltrating lymphocytes (TILs), including helper CD4+ T cells, cytotoxic CD8+ T cells, B cells and natural killer (NK) cells, and ultimately the effectiveness of immunomodulatory strategies." (PMID 36159809, 2022). "Within the CRC TME, tumor-infiltrating lymphocytes (TILs) consist of a heterogeneous mixture of adaptive immune cells composed of mainly anti-tumor effector T cells (CD4+ and CD8+ subpopulations), and suppressive regulatory CD4+ T (Treg) cells." (PMID 35874729, 2022). "Because of its direct cytotoxicity, CD4+ T cell-mediated tumour killing has emerged as a unique mechanism of anti-tumour immunity." (PMID 36159866, 2022). "A large variety of tumor-infiltrating immune cells, including CD4+ and CD8+ T lymphocytes, regulatory T cells (Tregs), B cells, Th17 cells, NK cells, DCs, MDSCs and neutrophils, interact with tumor cells in a complex way, mediated by the TME." (PMID 35965494, 2022). "TGF-β and IL-10 expression decrease synthesis of IFNγ and TNF-α by pro-inflammatory CD4 T cells, and in turn reduce tumor-specific cytotoxicity of CTLs, prevent activities of dendritic cells and NK cells, and result in tolerance to tumor cells." (PMID 35372046, 2022). "FACS analysis showed that 50% of the T cells recruited to MB49 tumor-implanted tissue were CD4 + helper T cells and < 10% were CD8 + lymphocytes." (PMID 35787261, 2022). "By directly inhibiting cell cycle of tumor cells, which is a novel antitumor immune mechanism, the antitumor effects of CD4+ T cells have been reported recently." (PMID 36262352, 2022). "A single systemic immune cell transfer into 5 Gy irradiated cachectic DBA/2 mice bearing up to 4 week established syngeneic tumors and macrometastases led to massive infiltration of tumor tissue by CD4+ and CD8+ donor T lymphocytes." (PMID 36361831, 2022). "The tumor Ag specificity of CD39+ tumor-infiltrating CD4 T cells was also demonstrated in human-papillomavirus (HPV)-induced malignancies." (PMID 35954341, 2022). "The only T cell subset which correlated with a reduction in tumor growth was within Tocky signal positive conventional CD4+, supporting their therapeutic role." (PMID 35338089, 2022). "The ability to modulate antigen presentation in transmissible cancer cells in the context of MHC uncovers additional targets for anti-tumour immune response and the potential for recruitment of CD4+ T cell help." (PMID 36259237, 2022). "Mechanistically, locally generated C3a and C5a signalled via their receptors on CD4+ T cells to promote anti-tumor immune responses." (PMID 35860237, 2022). "Tumor immunofluorescence showed that CD4+ T and CD8+ T cells were also increased in the tumor, and the innate immune and adaptive immune responses remained consistent, interacting to achieve an effective antitumor effect." (PMID 35875081, 2022). "In contrast, in stage III tumor tissues, weakly expressed CD4 was noticed in majority of the samples (80%, 12/15), which was significantly higher than the percentage of samples with strong expression of CD4 (20%, 3/15, P < 0.01)." (PMID 35187162, 2022). "The transferred tumor-specific CD4+ T cells also significantly reduced liver metastasis, demonstrating that the effect of the tumor-specific CD4+ T cells on metastasis was a general phenomenon." (PMID 35784297, 2022). "Using flow cytometry analysis, we confirmed the successful depletion of CD4+ T cells in dLN and tumor tissue and observed an increase of CD8+ T cell frequencies and numbers, which was significantly less pronounced in dLNs and tumors of Asm-KO mice." (PMID 36426850, 2022). "The CD4 T cells induced a transcriptional and functional switch in the TAMs, converting them from tumor-nurturing macrophages to inflammatory macrophages." (PMID 35903540, 2022). "Although CD4+ T cells cannot directly kill tumor cells, CD4+ T cells can play an indirect role in the TIME." (PMID 35126514, 2022).
tumor (continued). "Anti-CTLA-4 antibody enhances IL-36 stimulated anti-tumor activity by consuming Tregs, leading to increased CD4+ and CD8+T cells proliferation and IFN-γ levels." (PMID 35874717, 2022). "We have previously determined frequencies of different CD4+ T cell subsets in peripheral blood mononuclear cells (PBMCs), normal tissue-infiltrating lymphocytes (NILs), and tumor-infiltrating lymphocytes (TILs) of CRC patients." (PMID 36146549, 2022). "When an immunoscore was created based on the combination of individual CD4 and FoxP3 intraepithelial TC scores, this score was found to be correlated to tumor progression." (PMID 36177667, 2022). "Previous research has also established that DDX3X-primed CD4(+) T cells produced CD133(+) tumor-specific IFN-γ and IL-17 and mediated potent antitumor therapeutic efficacy." (PMID 35178128, 2022). "In prostate cancer, it increases Treg expression, promotes proliferation of myeloid-derived inhibitory cells (MDSCs), angiogenesis, and tumor progression and inhibits CD4+ and CD8+ T lymphocyte levels." (PMID 35719927, 2022). "Overall, NEO increased the proinflammatory function of tumor-infiltrating CD4+ T cells, with enhanced TNF-α and IL-2 but reduced IL-4 and IL-10 expression." (PMID 36509285, 2022). "This combination upregulated type I interferon response and MHC class I and PD-L1 on the tumour cell surface and increased PD-1 CD4+ and CD8+ T-cells, indicative of a possible response to immunotherapy." (PMID 35073851, 2022). "Altogether, these data suggest that CD4+ Treg utilize granzyme and perforin pathways to suppress anti-tumor responses in vivo." (PMID 35493508, 2022). "As a result of the ablation of autophagy genes in Treg cells, fewer cells were produced, which led to an increase in the number of effectors CD8+ and CD4+ T cells infiltrating the tumor, resulting in increased tumor resistance." (PMID 35912261, 2022). "Melanoma cells expressing MHC class II attract the infiltration of tumor-specific CD4+ T cells, possibly through interactions with LAG-3, which in turn negatively affects the CD8+ T cell response." (PMID 36077354, 2022). "Previous research has suggested that tumor-infiltrating CD4+ T cells can upregulate the immune checkpoint genes." (PMID 36147502, 2022). "This analysis revealed that proliferating Ki67+CD3+CD8+ and Ki67+CD3+CD4+ T cells were in close proximity to CAIX-expressing tumor cells." (PMID 36185254, 2022). "Meanwhile, antitumor immunosuppression mediated by CD4+ Treg cells is the primary mechanism of tumor immune evasion and immunotherapy resistance." (PMID 35432631, 2022). "The analysis of tumor-infiltrating lymphocytes showed that the therapeutic effect was related to the ratio of CD8+ Treg cells to CD4+FoxP3-Treg in the primary renal tumor, proving that VTP with the photosensitizer WST11 can induce a local immune response." (PMID 35832074, 2022). "There are many differences in gene expression within T-cell clusters, suggesting that T-cell biology in tumor tissues differs from that in paracancer tissues, especially in CD4+ T cells." (PMID 36466840, 2022). "In another study, vaccination of mice with an irradiated GM-CSF transduced MHC-I-negative tumor vaccine (B78H1-GM-CSF) protected mice against MHC-I-negative tumor challenge, and depletion of either CD4+ T cells or NK cells completely abrogated tumor rejection." (PMID 36159781, 2022). "First, the ratio of monocytes, NK cells (activated), T follicular helper (Tfh) cells, naive CD4+ T cells, memory B cells, and naive B cells were substantially lower in tumor cases with high SPTSSA expression." (PMID 36062185, 2022). "In NSCLC patients, the phenotyping of CD161+ T cells identified a higher frequency of CD161-expressing CD4+ T cells infiltrating the tumor compared to distant lung, draining lymph node and blood." (PMID 35185935, 2022). "Expression of both enzymes correlated with tumor-infiltrating DCs, CD4+ and CD8+ T cells, neutrophils, and macrophages." (PMID 35163211, 2022).